HDAC6 (histone deacetylase 6)
Diseases named in the same sentence as HDAC6 in open-access papers (continued):
Sharing a sentence is not in itself a finding about the gene and the disease.
multiple myeloma (continued). "Interestingly both HDAC6 and 7 exert immune-modulatory effects in myeloma but have not been specifically studied in the context of bortezomib refractory disease." (PMID 34888496, 2021). "In addition, MO-OH-Nap did not alter the levels of acetylated alpha-tubulin in myeloma cell lines, further suggesting that HDAC6 activity is not altered." (PMID 29100294, 2017). "Although HDAC6 activity does not drive tumour cell proliferation, HDAC6 has been shown to regulate the response to misfolded protein stress and its inhibition has synergistic effects with Bortezomib, which is administered in relapsed multiple myeloma." (PMID 18000499, 2007).
melanoma (61 papers, 2015 to 2025). A malignant, usually aggressive tumor composed of atypical, neoplastic melanocytes. "Targeting HDAC6 in melanoma can up-regulate the expression of tumor-associated antigens and MHC-I molecules leading to enhance anti-tumor immunity." (PMID 34880761, 2021). "Specific inhibition of class IIb HDAC6 can also increase tumor associated antigen production, such as gp100, Mart1 and Tryp1/2 in both human and murine melanoma cells." (PMID 26426052, 2015). "To further determine how these cancer-derived mutations affect endogenous HDAC6 abundance, we generated a melanoma cell line (WM2664) stably expressing SPOP WT or cancer-derived mutants including F102C, W131G, F133L, as well as empty vector (EV) as a negative control." (PMID 28599312, 2017). "We believe that both HDAC5 and HDAC6 could be good diagnostic and therapeutic targets for controlling melanoma." (PMID 26747087, 2016). "Our aim was to investigate whether HDAC6 has a biological role in human melanoma development and to understand its underlying mechanism." (PMID 25774669, 2015). "Therefore, our results suggested that the main cause of HDAC6 knockdown-induced melanoma cell apoptosis was ROS." (PMID 25774669, 2015). "Therefore, the purpose of this study was to observe the effect of HDAC6 in human malignant melanoma cell and to characterize the underlying molecular mechanisms via the ROS-mediated apoptosis by observing a series of cellular apoptotic pathways including mitochondrial function." (PMID 25774669, 2015). "For example, inhibiting HDAC6 can activate PD-L1 expression in melanoma, and abnormal KMT2A methylation promotes pancreatic cancer development." (PMID 40003691, 2025). "Other authors demonstrated that knocking down HDAC5 or HDAC6 inhibited melanoma cell proliferation and promoted apoptosis." (PMID 38542774, 2024). "HDAC6 is a member of the class IIb family of HDAC enzymes that regulate PD-L1 expression in melanoma, osteosarcoma, and chronic lymphocytic leukemia." (PMID 38747592, 2024). "Regarding the study on the regulation of PD-L1 expression by HDAC6, it has been reported that when HDAC6 is highly expressed in melanoma, p-STAT3 and HDAC6 bind the promoter of PD-L1, promoting the transcription of PD-L1." (PMID 38231305, 2024). "Altogether, our results suggest that HDAC6 plays a role in regulating CD47 expression in melanoma cells and that HDAC6i can prevent IFNγ-driven upregulation of CD47." (PMID 38414061, 2024). "As shown in this study, HDAC6 inhibition enhances phagocytosis of SM1 melanoma cells, an event regulated by the CD47/SIRPα axis." (PMID 38414061, 2024). "Preclinical studies have demonstrated that HDAC6 inhibition enhances the efficacy of anti-PD-1/PD-L1 immunotherapy in cancers such as melanoma, ovarian cancer, chronic lymphocytic leukemia, and colorectal cancer." (PMID 39063958, 2024). "Overall, the NSG-SGM3 model with a humanized immune system recapitulated the observations in SM1 murine melanoma model supporting HDAC6 inhibitor-treated M1 macrophages as a potential cell therapy to treat solid tumors." (PMID 39272209, 2024). "Evidence directly suggests that in human melanoma cells that highly express HDAC6, knockdown triggers marked ROS production and a decrease in mitochondrial membrane potential." (PMID 36749475, 2023). "Nexturastat A (Nex A) is a selective inhibitor of HDAC6 that was first investigated in melanoma and showed antitumor activity in in vitro and in vivo experimental models." (PMID 38258065, 2023). "Recent reports have shown that HDAC6 plays an essential role as a checkpoint regulator in melanoma cells." (PMID 36595522, 2023). "In melanoma-derived A375.S2 cells, the depletion of HDAC6 triggers the production of ROS and damages the mitochondrial membrane potential." (PMID 36749475, 2023). "Targeting HDAC6 helps to achieve a pronounced delay of in vivo melanoma tumor growth that partly depends on an intact immunity." (PMID 35693795, 2022).
melanoma (continued). "ACY-1215 and tubastatin A are selective inhibitors of HDAC6, which are required for the proliferation and metastasis of melanoma cells." (PMID 36532053, 2022). "HDAC6 binds to tubulin β3 and confers resistance to microtubule-targeting anti-cancer drugs in melanoma cells." (PMID 36076996, 2022). "Inhibition of HDAC6 in melanoma cells resulted in the increased expression of MHC class I and presentation of tumor-related antigens." (PMID 36012642, 2022). "Selective inhibitors of HDAC6 enhance T cell immune properties in melanoma patients, providing a theoretical basis for further studies to evaluate the potential clinical efficacy thereof." (PMID 35585975, 2022). "In an SM1 murine melanoma model, the HDAC6 inhibitor greatly reduced PD-L1 and PD-L2 overexpression, which increased the overall survival rate." (PMID 35585975, 2022). "In fact, HDAC6 plays a key role as an immune checkpoint regulator in primary human melanoma cells and the selective inhibition of HDAC6 isoform modulates Treg cells, enhancing their regulatory activity." (PMID 35592335, 2022). "Tubastatin‐A, Ricolinostat and Vorinostat significantly inhibit HDAC6/7 pathways that are involved in tumour proliferation and migration in CAFs and melanoma cells." (PMID 35731974, 2022). "For example, HDAC6 confers resistance to temozolomide in glioblastoma, and the HDAC6-selective inhibitor ACY-1215 accelerates vemurafenib-induced cell death of BRAF-mutant melanoma cells." (PMID 34746935, 2021). "Several studies have reported that inhibition of HDAC6 decreases expression of PD-L1 in glioblastoma and melanoma." (PMID 34880761, 2021). "Among the HDACs involved in cancer development, HDAC6 has caught the attention of many scholars, and recently, it has been shown to be related to melanoma onset." (PMID 34725562, 2021). "In melanoma HDAC6, via the tyrosine phosphatase PTPN1 and enhanced ERK1/2 activity, has been proposed to enhance proliferation." (PMID 33898322, 2021). "The HDAC6 inhibitor ACY-1215 sensitized melanoma cells to vemurafenib by inactivating ERK and promoting endoplasmic reticulum stress." (PMID 34944799, 2021). "HDAC6 causes STAT3 phosphorylation, where HDAC6 and phospho-STAT3 are then recruited to the CD274 promoter, mediating the upregulation of PD-L1 in melanoma." (PMID 34088360, 2021). "The INAPs functioned as effective epigenetic therapy agents by inhibiting the expression of pan-histone deacetylase (HDAC) and HDAC6-specific activity in melanoma cells in vitro." (PMID 31963449, 2020). "This study demonstrated that the use of HDAC6-specific inhibitors decreases immunosuppression and enhances immune function of melanoma patient T-cell giving a rationale for a potential translation into clinic." (PMID 32042336, 2020). "Histone deacetylase 6 (HDAC6) inhibition has been found to augment immunogenicity of melanoma cells through inhibition of STAT3-mediated PD-L1 transcription." (PMID 33329575, 2020). "HDAC6-specific inhibitors (Tubastatin A and Nexturastat) suppress melanoma cell proliferation by increasing the expression levels of tumor-associated antigens (TAAs) and human leukocyte antigen (HLA) class I." (PMID 32626712, 2020). "Other groups have also demonstrated that HDAC6 promotes melanoma proliferation and migration, suggesting its potential as a therapeutic target to control tumor growth." (PMID 31963449, 2020). "Our findings thus far have demonstrated that the INAPs retain their PTT properties as well as their ability to inhibit HDAC6 expression in melanoma cells (SM1 and B16F10) in vitro." (PMID 31963449, 2020). "Previous studies have demonstrated tumor immunomodulation of immune markers, such as MHC-I, in melanoma cells after treatment with HDAC6 inhibitor." (PMID 31963449, 2020). "HDAC6, which is highly expressed in various melanoma cells, is necessary for invasion and metastasis of melanoma cells." (PMID 32626712, 2020).
melanoma (continued). "The INAPs were able to inhibit HDAC6-specific activity as evidenced by the increased expression of Ac-α-tubulin in melanoma cells in vitro relative to controls." (PMID 31963449, 2020). "To better understand the impact of HDACi on human T-cells, we analyzed the effects of selective HDAC6 inhibition ex vivo on the immune properties of T-cells derived from melanoma patient peripheral blood mononuclear cells (PBMC) and tumor biopsies." (PMID 30728070, 2019). "HDAC6-selective inhibitors augmented melanoma patient T-cell immune properties, providing a rationale for translational investigation assessing their potential clinical efficacy." (PMID 30728070, 2019). "The ability of compound 4f to inhibit HDAC6 was confirmed by western blot analyses as well as by immunofluorescence staining of acetyl–alpha-tubulin in 518A2 melanoma cells." (PMID 30658435, 2019). "Recent reports have shown that HDAC6 plays a critical role as an immune checkpoint regulator in primary human melanoma cells." (PMID 30992475, 2019). "Collectively, these results demonstrate novel effects of HDAC6-selective inhibition on the phenotype and function of melanoma patient T-cells." (PMID 30728070, 2019). "Previous reports have shown inhibition of HDAC6 leads to decrease immunosuppression and enhance T-cell immune properties in melanoma patient cells." (PMID 31652644, 2019). "Some studies have reported the overexpression of HDAC6 in bladder cancer, malignant melanoma, and lung cancer." (PMID 30176876, 2018). "The increased gene expression of RGD4C-AAVP to melanoma M21 cells therefore perhaps represent the ability of C1A to inhibit an HDAC6-mediated host-defense against invading foreign proteins." (PMID 29690504, 2018). "We tested the effects on melanoma, known for HDAC6 up-regulation, and compared this side by side with a normal human kidney HEK293 cell line." (PMID 29690504, 2018). "Subsequently, we have presented a novel strategy to improve RGD4C-AAVP gene transfer to melanoma, specifically and other cancers that express HDAC6, by combining RGD4C-AAVP with selective inhibition of HDAC6 by using the C1A inhibitor." (PMID 29690504, 2018). "Because HDAC6 is required for proliferation of melanomas we used M21, a human melanoma cell line reported to express the αvβ3 integrin receptor of the RGD4C-AAVP." (PMID 29690504, 2018). "In melanoma cells knock down of [HDAC6 + HDAC2] or [HDAC6 + HDAC10] significantly enhanced pazopanib lethality whereas knock down of [HDAC6 + HDAC1] or [HDAC6 + HDAC3] were less effective." (PMID 29137331, 2017). "The alterations observed in autophagosome formation were also reflected in the ability of [pazopanib + AR42] to kill the melanoma cells, with expression of wild type HDAC6 reducing killing and expression of dominant negative HDAC6 promoting death." (PMID 28146421, 2017). "Treatment of vemurafenib resistant TPF-12-293 melanoma cells with [pazopanib + AR42] promoted the co-localization of HDAC6 with LAMP2." (PMID 29137331, 2017). "In most samples, the levels of total HDAC5 and HDAC6 were higher in melanoma tissues than normal skin tissues." (PMID 26747087, 2016). "In this present study, we showed that knockdown of HDAC5 or HDAC6 prevented proliferation and induced apoptosis of the melanoma cells." (PMID 26747087, 2016). "We used overexpression and knocking down lentivirus to clarify the influence of HDAC5 and HDAC6 in melanoma development." (PMID 26747087, 2016). "When tested for expression levels, both HDAC5 and HDAC6 had higher protein levels in melanoma cells (M257, SK-MEL-28, A375 and A2058 cells) than normal skin cells (HaCaT)." (PMID 26747087, 2016). "We presented both HDAC5 and HDAC6 as tumor promoters in melanoma proliferation and metastasis through different signaling pathway, and shaded some light on the potential mechanisms." (PMID 26747087, 2016).
melanoma (continued). "This study demonstrated both HDAC5 and HDAC6 were required for melanoma cell proliferation and metastasis through different signaling pathways." (PMID 26747087, 2016). "We used CCK8 to identify cell proliferation after reducing HDAC5 or HDAC6 expression levels in melanoma cells." (PMID 26747087, 2016). "In this study, and found that HDAC5 and HDAC6 were highly expressed in melanoma cells but exhibited low expression levels in normal skin cells." (PMID 26747087, 2016). "For clarifying the sublocations of HDAC5 and HDAC6 in melanoma tissues, we then performed immunohistochemistry in 10 clinical melanoma samples, including 46 samples that had the adjacent normal melanoma tissues." (PMID 26747087, 2016). "In present study, we reported that HDAC6 expression was up-regulated in melanoma tissues and several melanoma cell lines, suggesting that this protein contributes to the highly active metabolism of melanoma." (PMID 25774669, 2015). "We also analyzed HDAC6 expression in several melanoma cell lines by quantitative real time PCR (qRT-PCR) and Western blot." (PMID 25774669, 2015). "In conclusion, the results showed that knockdown of HDAC6 induced apoptosis in human melanoma A375.S2 cells through a ROS-dependent mitochondrial pathway." (PMID 25774669, 2015). "HDAC6 expression in human malignant melanoma (n = 23) and its adjacent, normal cancer dermatic tissue (n = 23) was assayed by Western blot." (PMID 25774669, 2015). "Our results revealed that HDAC6 siRNA significantly inhibited melanoma cell proliferation and clone formation abilities, and arrested cell cycle in G0/G1 phase." (PMID 25774669, 2015). "We found that HDAC6 protein expression was significantly up-regulated in malignant melanoma tissue, whereas weak expression was found in the adjacent, normal cancer dermatic tissue (***P < 0.001)." (PMID 25774669, 2015). "Experimental evidence indicates that the HDAC6/STAT3 axis regulates PD-L1 expression, suggesting that targeting the MIIP/HDAC6/PD-L1 pathway might enhance immune checkpoint inhibitor efficacy in melanoma." (PMID 40573881, 2025). "Genetic knockdown and pharmacologic inhibition by the HDAC6 inhibitors markedly reduced melanoma tumor growth and combination therapy further reduced tumor growth compared with the individual effect of either agent and led to a greater infiltration of activated cytotoxic T cells." (PMID 38747592, 2024). "Similarly, histone deacetylase 6 (HDAC6) inhibitors with enhanced antitumor immunity of anti-PL-L1 immunotherapy were recently developed for melanoma treatment." (PMID 36600243, 2023). "Previous studies have revealed that HDAC6 inhibitors might suppress the growth of a panel of human melanoma cell lines and could be a potential strategy for melanoma therapy, even resolving vemurafenib resistance." (PMID 36532053, 2022). "The combination of the HDAC6 inhibitor nexturastat and an anti-PD-1 antibody induced anti-tumor immune responses in syngeneic melanoma tumor models by increasing the infiltration of immune cells, increasing central and effector T cell memory, and decreasing pro-tumorigenic M2 macrophages." (PMID 36076996, 2022). "Therefore, the observation that HDAC6-selective inhibitor augments T-cell immune properties in melanoma patients provides a rationale for translational investigation of their potential clinical efficacy." (PMID 35693795, 2022). "Histone deacetylase 6 (HDAC6), which has the potential to be a predictive biomarker for melanoma and ovarian cancer, also regulates epigenetic resistance to PD-1 immunotherapy in melanoma patients." (PMID 36384676, 2022). "Combining Nexturastat (HDAC6 inhibitor) with an anti-PD-1 agent has been reported to suppress tumor growth, decrease the level of pro-tumorigenic M2 macrophages and upregulate effector T cells in melanoma." (PMID 35585975, 2022). "HDAC6 promotes the invasion and metastasis of melanoma cells." (PMID 36076996, 2022).